GLA (galactosidase alpha)
Diseases named in the same sentence as GLA in open-access papers (continued):
Sharing a sentence is not in itself a finding about the gene and the disease.
Fabry disease (continued). "Fabry disease (FD) is a rare lysosomal storage disorder caused by mutations in the GLA gene, resulting in reduced or lack of α-galactosidase A activity." (PMID 37670295, 2023). "Fabry disease (FD; OMIM #301,500) is a rare X-linked inherited lysosomal storage disorder resulting from absent or markedly reduced activity of the α-galactosidase A (α-Gal-A) enzyme due to mutations in the GLA gene (OMIM #300,644)." (PMID 37097439, 2023). "Fabry disease (FD) is an X-linked inborn error of glycosphingolipid catabolism caused by deleterious mutations in the α-galactosidase A gene (GLA) encoding the lysosomal hydrolase, alpha-galactosidase A (α-Gal A)." (PMID 36143092, 2022). "Fabry disease (FD; OMIM #301500) is an X-linked (Xq22.1) inborn error of glycosphingolipid catabolism resulting from deficient α-galactosidase A activity (AGAL; 300644) due to mutations in the GLA gene." (PMID 36569886, 2022). "Fabry disease (FD) is an X-linked inborn error of glycosphingolipid catabolism that is caused by deleterious mutations in the GLA gene encoding the lysosomal hydrolase, alpha-galactosidase A (α-Gal A)." (PMID 35268433, 2022). "Fabry disease (FD, OMIM #301500) is an X-linked inherited metabolic disease due to the deficiency of lysosomal-galactosidase A activity (GalA-EC 3.2.1.22), which is encoded by the GLA gene." (PMID 36005574, 2022). "Fabry disease (FD) is a rare, X-linked, multisystemic lysosomal storage disorder (LSD) that results from a deficiency in the hydrolase alpha-galactosidase A (⍺-GalA) caused by a GLA gene mutation." (PMID 34118938, 2021). "Fabry disease (FD) is an X-linked recessive lysosomal storage disease caused by a mutation of the galactosidase alpha (GLA) gene, leading to deficiency of α-galactosidase A (alpha-Gal A)." (PMID 32699723, 2020). "Fabry disease (FD) is an X-linked lysosomal disorder caused by mutations in GLA gene resulting in lack of or faulty α-galactosidase A (α-GalA) enzyme." (PMID 33003611, 2020). "We also elucidate the effect of amiloride to modulate GLA (IVS4+919G>A) splicing through a PP1 dependent manner, and suggest its role in the treatment of the specific genetic type of Fabry disease." (PMID 28430823, 2017). "Our findings revealed the alternative splicing mechanism of GLA (IVS4+919G>A), and a potential treatment for this specific genetic type of Fabry disease by amiloride in the future." (PMID 28430823, 2017). "These significant findings reveal the alternative splicing mechanism of GLA (IVS4+919G>A), and a potential treatment for this specific genetic type of Fabry disease." (PMID 28430823, 2017). "Fabry disease (FD, OMIM 301500) is a rare X-linked lysosomal storage disorder caused by deficiency of the lysosomal enzyme alpha galactosidase A (aGAL, enzyme commission number: 3.2.1.22) due to mutations in the GLA gene (Xq22.1)." (PMID 28763515, 2017). "In addition, this in vitro Fabry disease (FD) model provides a precedent for the genesis of other GLA-null human cells from different cell types including primary human stem cells." (PMID 27983599, 2016). "Fabry disease (FD; OMIM #301500) is an X-linked (Xq22.1) inborn error of glycosphingolipid degradation resulting from deficient α-galactosidase A activity (GLA; 300644) due to mutations in the GLA gene." (PMID 27356758, 2016). "α-Gal A is encoded by the GLA gene and mutations in this gene causes deficiency or absence of the enzyme, resulting in Fabry disease (FD) (OMIM 301500), an X-linked inherited lysosomal storage disorder." (PMID 26334996, 2015). "Fabry disease (FD) is a multisystemic disorder with typical neurological manifestations such as stroke and small fiber neuropathy (SFN), caused by mutations of the alpha-galactosidase A (GLA) gene." (PMID 25423912, 2014). "Fabry disease (FD, OMIM 301500) is a rare inherited storage disorder caused by mutations in the GLA gene (located at Xq22) that result in deficient or absent lysosomal α-galactosidase A (GLA) activity." (PMID 41516147, 2025).
Fabry disease (continued). "Anderson-Fabry disease (AFD) is an X-linked lysosomal storage disorder caused by pathogenic variants in the α-galactosidase A gene (α-GAL-A, GLA gene), resulting in reduced or absent lysosomal enzyme activity and impaired lysosomal function." (PMID 39125842, 2024). "Fabry disease (FD), a lysosomal storage disorder characterized by a lack of the enzyme alpha-galactosidase A due to different variants of the GLA gene, typically leads to structural changes within the cells and tissues of affected organs, including the heart, the kidneys, and the nervous system." (PMID 36855009, 2023). "Here, we explored five distinct glycoforms of GLA, including two lacking M6P or exposed Man residues in a Fabry disease mouse model, and found significant changes in circulation half-life and biodistribution." (PMID 31040271, 2019). "Electron microscopic examination revealed numerous membranous inclusion bodies in podocytes, and biochemical analysis revealed normal GLA activity and a normal lyso-Gb3 level in plasma, showing that they did not have Fabry disease." (PMID 26312237, 2015).
lysosomal storage disorder (115 papers, 2010 to 2026). "It is a multisystem, progressive lysosomal storage disorder caused primarily by mutations in the galactosidase alpha (GLA) gene." (PMID 40135233, 2025). "Anderson–Fabry disease (AFD) is a lysosome storage disorder resulting from an X-linked inheritance of a mutation in the galactosidase A (GLA) gene encoding for the enzyme alpha-galactosidase A (α-GAL A)." (PMID 38248084, 2024). "Anderson–Fabry Disease (AFD) is a rare, systemic lysosomal storage disease triggered by mutations in the GLA gene, leading to α-galactosidase A (α-Gal A) deficiency." (PMID 37761944, 2023). "Fabry disease (FD) is a rare X-linked lysosomal storage disorder caused by a variety of mutations in the alpha-galactosidase gene (GLA) on Xq21.3-q22." (PMID 35242583, 2022). "Fabry disease (FD) is a rare X-linked lysosomal storage disorder caused by disease-associated variants in the alpha-galactosidase A gene (GLA)." (PMID 34905550, 2021). "FD is an X-linked recessive lysosomal storage disorder caused by deficiency of the enzyme α-Gal A secondary to GLA gene mutations." (PMID 30587147, 2018). "FD is a rare lysosomal storage disorder caused by mutations in the GLA gene on the X chromosome." (PMID 40520931, 2025). "FD is an inherited lysosomal storage disorder linked to the X chromosome caused by pathogenic variants in the galactosidase alpha (GLA) gene (Xq21.3-q22), leading to an absence or deficiency of alpha-galactosidase A enzyme (α-Gal A)." (PMID 40420145, 2025). "Pseudodeficiency variants were also identified in other lysosomal storage disorders, such as p.R247W and p.R249W in the HEXA gene, p.A300T in the IDUA gene, p.R595W in the GLB1 gene, p.D152N in the GUSB gene, and p.D313Y in the GLA gene." (PMID 40449593, 2025).
Stroke (18 papers, 2014 to 2025). Sudden impairment of blood flow to a part of the brain due to occlusion or rupture of an artery to the brain. "It is caused by mutations in the GLA gene resulting in deficiency of α-galactosidase A (α-Gal A), leading to peripheral neuropathy, cardiovascular disease, stroke, end-stage renal disease, gastrointestinal disorders and premature death." (PMID 37828551, 2023). "Thus, we have shown for the first time that there is significant association (p = 0.005) of the development of stroke in men with their genome containing nonsense and frameshift variants of the GLA gene." (PMID 38002959, 2023). "However, it was identified that men with nonsense and frameshift variants of the GLA gene exhibited a significant correlation (p = 0.005) with stroke." (PMID 38002959, 2023). "Three genes (orange), golgin subfamily B member 1 (GOLGB1), α-galactosidase A (GLA), and heme oxygenase-1 (HMOX1), are both SARS-CoV-2 host genes as well as stroke-associated genes." (PMID 33732102, 2021).
X-linked disease (16 papers, 2013 to 2026). X-linked form of disease. "It is currently recognized as the second most common LSD after Gaucher disease and is an X-linked inherited disorder caused by mutations in the galactosidase alpha (GLA) gene, located on the long arm of the X chromosome (Xq22.1)." (PMID 40806187, 2025). "FD is an X-linked disease in which mutations of the GLA gene result in a deficiency of the enzyme α-galactosidase A and subsequent progressive, intralysosomal deposition of undegraded glycosphingolipid products, primarily Gb3, in multiple organs." (PMID 26602202, 2015). "FD is an X-linked inherited disorder of the glycosphingolipid metabolism, caused by a variety of mutations in the alpha-galactosidase A gene (GLA), resulting in progressive accumulation of globotriaosylceramide, especially in endothelial cells, causing multi-organ damage." (PMID 37893091, 2023). "FD is a progressive, X-linked inherited disorder of glycosphingolipid metabolism due to deficient or absent alpha-galactosidase-A (AGAL) activity caused by over 1000 known disease-associated variants in the GLA gene." (PMID 37480392, 2024).
cardiomyopathy (15 papers, 2015 to 2026). A disease of the heart muscle or myocardium proper. "WES was proposed by our cardiomyopathy center and, unexpectedly, a mutation [c.595T>C (p.Val199Met)] in exon 4 of the GLA gene was identified." (PMID 39650153, 2024). "The cardiomyocytes differentiated from these hESCs (GLA-null CMs) were characterized by the accumulation of Gb3 and significant increases of cell surface area, the landmarks of FD-associated cardiomyopathy." (PMID 30965672, 2019). "The GLA gene on the X‐chromosome is one of the genes on the cardiomyopathy gene panel associated with a phenocopy of a cardiomyopathy." (PMID 30847665, 2019). "Therefore, it is important to understand how GLA pathogenic variants and DNA methylation upregulate inflammatory genes within the context of cardiomyopathy." (PMID 40072051, 2025). "Given the fact that CM hypertrophy is one of the symptoms of FD-associated cardiomyopathy, we examined whether GLA-null CMs could recapitulate such features." (PMID 30965672, 2019). "In summary, we have shown that CRISPR/Cas9-edited hESC-derived GLA-null CMs recapitulated the typical phenotype features of FD-affected CMs and, therefore, could be a useful model to study the FD-associated cardiomyopathy." (PMID 30965672, 2019). "Therefore, these GLA-null CMs clones recapitulated the typical characteristics of FD-associated cardiomyopathy." (PMID 30965672, 2019). "Immunofluorescent staining of cardiac troponin T (cTnT) revealed that GLA-null CMs were of significantly larger size (26% ± 9.7%, p < 0.001) as compared to the control H9 CMs, which was consistent with the phenotype of FD-associated cardiomyopathy." (PMID 30965672, 2019). "Since the proteomic analysis revealed the downregulation of components of vesicular trafficking machinery in GLA-null CMs, we hypothesized that dysfunctional autophagy pathway may underlie the impairment of cellular homeostasis in FD-related cardiomyopathy." (PMID 30965672, 2019). "To summarize, both established GLA-null hESC clones exhibited normal stem cell properties, and therefore, were suitable for differentiation into FD-specific cardiomyocytes to investigate the mechanisms of involvement of GLA deficiency in the pathology of FD cardiomyopathy." (PMID 30965672, 2019). "The markedly reduced GLA enzyme level and elevated Lyso-GL-3 levels confirmed the diagnosis of FD cardiomyopathy." (PMID 39650153, 2024). "The inclusion of the GLA gene in cardiomyopathy genetic panels, combined with heightened clinical suspicion based on cardiac and extracardiac red flags, may enhance early diagnosis and appropriate management." (PMID 41153811, 2025). "Therefore, our strategy in this study was to generate GLA knockout in human pluripotent stem cells by CRISPR/Cas9-mediated gene editing, and compare them with the parental cells of the same genetic background to study the mechanisms of FD-associated cardiomyopathy." (PMID 30965672, 2019). "The mean (±SD) number of genes per panel was 33±25, including 8±0.3 sarcomere genes, 4±2 storage cardiomyopathy, and RASopathy genes (LAMP2, PRKAG2, TTR, GLA, PTPN11, RIT1, and RAF1) and 22±23 other genes (range, 0–75)." (PMID 30681346, 2019).
renal failure (11 papers, 2007 to 2026). "FD is caused by mutations in the GLA gene, and it affects the body’s ability to break down Gb3, leading to various symptoms, including kidney failure and heart issues." (PMID 38540351, 2024).
chronic kidney disease (9 papers, 2018 to 2025). Impairment of the renal function secondary to chronic kidney damage persisting for three or more months. "A family is presented here with a 36‐year‐old female who is symptomatic with chronic kidney disease and her oligosymptomatic 70‐year‐old father, both of whom have a heterozygous and hemizygous GLA pathogenic variant, respectively, c.1087C>T (p.R363C)." (PMID 39822326, 2025). "In this study, we report a four-generation pedigree with left ventricular hypertrophy and chronic renal failure that was diagnosed by sequencing the GLA gene." (PMID 30587147, 2018). "Previous screening studies have shown that a significant proportion of end-stage renal disease (ESRD) patients receiving hemodialysis (HD) have unsuspected FD, and the prevalence of low alpha-galactosidase A (αGLA) enzyme activity in these patients is higher than that in the normal population." (PMID 32997080, 2020).
left ventricular hypertrophy (9 papers, 2018 to 2026). Enlargement of the LEFT VENTRICLE of the heart. "In particular, we evaluated the levels of the 10 microRNAs in the plasma samples of 10 subjects with left ventricular hypertrophy attributable to causes other than mutations in the GLA gene." (PMID 29937989, 2018). "Problematic is the diagnosis of atypical FD patients presenting with an uncharacteristic symptom (e.g., albuminuria, left ventricular hypertrophy or white matter lesions) in combination with an abnormality in the GLA gene with unknown consequences." (PMID 33673160, 2021).
cardiac hypertrophy (8 papers, 2007 to 2025). "Collectively, these data indicated to the recapitulation of cardiac hypertrophy and GLA enzymatic decrease in patient-derived FC-iPSC-CMs." (PMID 29772700, 2018). "Mutations in genes encoding the γ2 subunit of AMP-activated protein kinase (PRKAG2), α-galactosidase A (GLA), and lysosome-associated membrane protein-2 (LAMP2) can cause profound myocardial hypertrophy in association with electrophysiologic defects." (PMID 23700405, 2013). "In addition, GLA-null CMs were characterized by shifted balance between α- and β-cardiac myosin heavy chain (MYH6/MYH7 ratio) expression, which is a common response to cardiac injury and a hallmark of cardiac hypertrophy." (PMID 30965672, 2019).
hypertrophic cardiomyopathy (8 papers, 2016 to 2025). A condition in which the myocardium is hypertrophied without an obvious cause. "To summarize, in the present study we show that CRISPR/Cas9-mediated GLA knockout of hESC-derived CMs can serve as an in vitro FD model for studying hypertrophic cardiomyopathy." (PMID 30965672, 2019). "In this study, a screening for the GLA gene was performed in a groupof patients with echocardiographic diagnosis of hypertrophic cardiomyopathy(HCM)." (PMID 31291414, 2019).
angiokeratoma (7 papers, 2015 to 2026). A vascular lesion in the papillary dermis resulting from ectasia of pre-existing vessels. "Results from our group and others thus indicate that prevalence of angiokeratoma in FD patients varies significantly depending on mutations in the GLA gene and gender and this skin lesion occurs more commonly in men with FD than in women with FD." (PMID 29797054, 2018). "The classical and nonclassical phenotypes have been empirically determined on the basis of the presence or absence of characteristic symptoms (usually neuropathic pain, angiokeratoma, and cornea verticillata (CV)), GLA enzyme activity and/or the GLA genetic variant, though without any consensus." (PMID 32442237, 2020). "The diagnosis of classical FD in these patients is based on the presence of a GLA mutation, absent or very low residual enzyme activity, and the presence of at least one of the following: angiokeratoma, cornea verticillata, or a very high (lyso)Gb3 level." (PMID 25885911, 2015).
Danon disease (6 papers, 2018 to 2025). A lysosomal glycogen storage disease characterized by severe cardiomyopathy and variable degrees of muscle weakness, frequently associated with intellectual deficit. "Less frequent genetic causes are linked to infiltrative or metabolic diseases, such as GLA mutations in Fabry disease, TTR in transthyretin amyloidosis, LAMP2 in Danon disease, and PRKAG2 in glycogen storage cardiomyopathy." (PMID 40868441, 2025).
Alport syndrome (3 papers, 2020 to 2025). A rare renal disease characterized by glomerular nephropathy with hematuria progressing to end-stage renal disease (ESRD), frequently associated with sensorineural deafness, and occasionally with ocular anomalies. "However, subsequent whole-exome sequencing revealed a c.3209C > T mutation in the COL4A3 gene, confirming Alport syndrome, while no mutation was detected in the GLA gene." (PMID 41516147, 2025).
diabetes (3 papers, 2010 to 2023). "A deficiency of GLA, DGLA, AA, EPA, and DHA due to low activity of desaturases increases the rigidity of cell membrane, as seen in those with diabetes mellitus, hypertension, and coronary heart disease, who have decreased plasma and tissue concentrations of GLA, DGLA, AA, EPA, and DHA." (PMID 34944517, 2021).
glioma (3 papers, 2023 to 2026). A benign or malignant brain and spinal cord tumor that arises from glial cells (astrocytes, oligodendrocytes, ependymal cells). "Upregulation of alpha-galactosidase A (GLA) is associated with poor prognosis and immune infiltration in glioma." (PMID 38786019, 2024). "In glioma cell lines, GLA knockdown suppressed cell viability and downregulated EDEM2." (PMID 41952691, 2026).
melanoma (3 papers, 2021 to 2024). A malignant, usually aggressive tumor composed of atypical, neoplastic melanocytes. "GlA is extracted from Glycyrrhiza glabra and demonstrates significant anti-tumor activity against melanoma by targeting the tumor microenvironment (TME) and modulating immune responses." (PMID 38338469, 2024). "When combined with Mycobacterium indicus pranii (Mw), an immunomodulator, GlA shows enhanced effectiveness, particularly against advanced-stage melanoma." (PMID 38338469, 2024). "GlA’s mechanisms include inducing apoptosis in melanoma cells and reducing their proliferation." (PMID 38338469, 2024). "Additionally, our study identified genes without reported expression in CMM and nevi or biological function related to melanoma progression, including CCL3L3, NPY1R, IL11A, FCGR1B, OAS2, ASB11, FCGR3A, and GLA." (PMID 35008167, 2021).
sphingolipidosis (3 papers, 2019 to 2025). An inherited metabolic disorder that affects the lysosomal degradation of the spinhgolipids. "Fabry is an X-linked recessive sphingolipidosis caused by a deficiency in the lysosomal enzyme α-Galactosidase A due to mutations in the human GLA gene." (PMID 41511290, 2025). "Apart from the novel variants identified in the GLA gene, GM2A gene, and GALC genes, only one known GBA pathogenic variant was detected in Sphingolipidoses-related genes: the p.Leu483Pro in the GBA gene (patient P1)." (PMID 32883051, 2020).
Alzheimer disease (2 papers, 2024). A progressive, neurodegenerative disease characterized by loss of function and death of nerve cells in several areas of the brain leading to loss of cognitive function such as memory and language. "This research has identified several genes potentially involved in lipid metabolism in Alzheimer’s disease, including CHAT, RAB4A, ACBD6, and GLA." (PMID 39507054, 2024).